INS (insulin)
Diseases named in the same sentence as INS in open-access papers (continued):
Sharing a sentence is not in itself a finding about the gene and the disease.
Obesity (continued). "There is some evidence that co-therapies including CLA and insulin sensitizing agents could be a plausible strategy against obesity." (PMID 30754681, 2019). "Moreover, the deletion of GRK2 during a HFD restores a lean and insulin-sensitive phenotype, even after obesity and insulin resistance have been established." (PMID 31752326, 2019). "Researchers found that irisin were positively associated with fasting insulin and blood glucose in healthy individuals, and in women with polycystic ovary syndrome and in children with obesity but without T2DM." (PMID 31881940, 2019). "Furthermore, there is evidence that these genetic predispositions can be induced by environmental triggers (i.e. prenatal androgen exposure, obesity-related hyperinsulinemia and/or insulin injections)." (PMID 31367382, 2019). "These animals exhibited improved insulin sensitivity associated with increased CD206 expression in adipose tissue, independent of differences in ATM content, suggesting p110γ is dispensable for ATM recruitment but promotes M1 responses in obesity." (PMID 31497027, 2019). "However, excessive glucose can be converted into fatty acids and triglycerides in the liver and adipose tissue and increase insulin concentration, thereby inducing obesity and DM." (PMID 31885637, 2019). "Additionally, previous studies have reported that obesity from a HFD decreases the activity of the hippocampal insulin signaling pathway, including the activity of IRS-1, PI3K, p-PDK1, p-AKT, and p-GSK-3β." (PMID 31311133, 2019). "Although this study suggests that nuchal adiposity may be of greater interest in relation to ID than generalised obesity, obese ponies may still be insulin-dysregulated." (PMID 31339945, 2019). "In conclusion, EGCG may be useful to treat obesity by re-sensitizing insulin-resistant muscle, increasing muscle lipid oxidation and stimulating the glucose uptake of muscle cells." (PMID 30691224, 2019). "We generated HFD-induced obesity mice and performed glucose and insulin tolerance tests." (PMID 31133649, 2019). "Ideally, future studies would incorporate more comprehensive metabolic profiling (e.g., measures of insulin sensitivity) that would allow better insight as to how the phenomena of metabolic (ab)normality with obesity affects muscle protein synthesis responses to dietary protein and exercise." (PMID 31263701, 2019). "Ablation of NLRP3 enhances insulin signaling in a mouse model of obesity." (PMID 31461911, 2019). "Interestingly, when TNF-α was inhibited by a neutralizing antibody or genetic manipulation, different obesity model mice showed improved insulin sensitivity." (PMID 31405033, 2019). "In summary, ginsenoside Rb1 acts as an insulin sensitizer and thus has a hypoglycemic function and this compound may be developed as an anti-obesity, anti-hyperglycemic, and anti-diabetic agent." (PMID 30823412, 2019). "Obesity has long been defined by chronic inflammation and resistance to insulin." (PMID 31623075, 2019). "Insulin and insulin-like growth factor-1 stimulate specific responses in arteries, which may be disrupted by diet-induced obesity." (PMID 30295509, 2019). "Although there are three classes of PI3K enzymes, this mini-review will focus on class I PI3Ks and their function in macrophages in response to metabolic stimuli that are upregulated during obesity, including insulin, glucose, cholesterol and free fatty acids (FFAs)." (PMID 31497027, 2019). "In agreement with the results from recent clinical studies, we found that carvedilol treatment during HFD-induced obesity improved glucose tolerance and insulin sensitivity possibly by suppressing the hepatic glucose overproduction and enhancing the muscular insulin signaling pathway." (PMID 31682617, 2019).
Obesity (continued). "We assessed the therapeutic potential of the strongest anti-inflammatory compound, indigo, in the C57BL/6J diet-induced obesity mouse model with supplementation for up to 16 weeks by measuring changes in body weight, glucose and insulin tolerance, and gut barrier function." (PMID 30944419, 2019). "However, adipose tissue and muscle also act as endocrine organs that release various cytokines, such as leptin, adiponectin, tumor necrosis factor-alpha, and interleukin-6, and alter insulin sensitivity in obesity and metabolic syndrome." (PMID 31470507, 2019). "In the multivariate models, though we used the presence of metabolic syndrome and obesity as possible surrogates of hyperinsulinemia, measurement of insulin would be needed in a future study to carefully investigate the relationship between OSA and adrenal size or the HPA axis." (PMID 31539392, 2019). "However, NAFL and NASH are diseases of the liver and also tightly coupled to obesity, adipose tissue dysregulation, and reduced insulin sensitivity." (PMID 31214196, 2019). "It is increasingly accepted that impaired insulin signaling could affect metabolic changes in various tissues during obesity." (PMID 31379826, 2019). "The changes in insulin sensitivity through pregnancy are believed to be caused partly by hormones from the placenta and partly by other obesity- and pregnancy-related factors that are not fully understood." (PMID 31828161, 2019). "Protection against HFD-induced obesity is effective in improving peripheral insulin sensitivity." (PMID 31394876, 2019). "Thus, the dysregulated state of glucose and insulin often seen in obesity can be corrected with both hypocaloric diets and LCHF diets." (PMID 31920704, 2019). "Therefore, this study sought to elucidate the insulin sensitizing and anti-obesity effects of WFA in diet-induced obese C57BL/6J mice and 3T3- F442A adipocytes." (PMID 31226166, 2019). "To study the systems-wide molecular changes associated with obesity-dependent IR, we integrated information on plasma proteins and microRNAs in eight obese insulin-resistant (OIR, HOMA-IR > 2.5) and nine lean insulin-sensitive (LIS, HOMA-IR < 1.0) normoglycemic males." (PMID 31024340, 2019). "The development of central resistance to the effect of insulin, leptin as well as other hormones effective on energy metabolism and chronically altered in obesity may also explain the BMI-related differences in brain glucose metabolism." (PMID 31600734, 2019). "Changes in insulin secretion are closely related to obesity." (PMID 31195699, 2019). "The rise in overweight and obesity may be related to intensive insulin therapy coupled with a positive energy balance." (PMID 31067747, 2019). "The expression of ARHGEF11 was significantly higher in the livers of the F2G♀C♂ and F2G♀G♂ groups, and insulin signaling molecules were accordingly suppressed, which may explain an influential factor for obesity in F2 offspring." (PMID 31612150, 2019). "These evidences strongly support the existence of a strict link between testosterone levels and insulin sensitivity, not necessarily correlated with underlying obesity." (PMID 31402895, 2019). "Insulin action and often glucose-stimulated insulin secretion are reduced in obesity." (PMID 31949886, 2019). "Overall, our results suggest that insulin could exert a thermogenic effect independently of obesity levels, possibly by direct interaction with warm-sensitive neurons stimulating active brown adipose tissue (BAT)." (PMID 30250242, 2019). "For example, Enterobacter cloacae produces endotoxins, causing non-obese aseptic mice to develop severe obesity, inducing inflammation and insulin resistance in mice, downregulating genes involved in fat catabolism, and activating lipogenesis genes." (PMID 30814920, 2019). "This clearly indicated that the increase in Enterobacteriaceae in MSTN-/- Meishan pigs did not cause obesity or a decrease in insulin sensitivity." (PMID 30645618, 2019).
Obesity (continued). "Interestingly, in vitro studies have shown that β-cells have an exceptional capacity to synthesize significant amounts of insulin even in obesity-like conditions, and that this insulin is readily available for secretion." (PMID 31178685, 2019). "Likewise, the L. casei Shirota strain also increased the insulin sensitivity and decreased the glucose intolerance of mice with diet-induced obesity." (PMID 31623075, 2019). "Here, we determined whether mirabegron treatment stimulated mast cell degranulation in the same cohort of insulin resistant research participants with obesity (see6 for baseline characteristics)." (PMID 31209239, 2019). "Those using measurement of sympathetic reactivity as reflected by levels of catecholamines in serum or urine after provocation by mental stress, cold stress or food intake have found some correlation to obesity, future development of obesity and insulin resistance." (PMID 31133864, 2019). "Obesity could affect the metabolism in the body by insulin resistance and reducing insulin secretion." (PMID 31149032, 2019). "MiR-30a could remodel subcutaneous adipose tissue inflammation to improve insulin sensitivity in obesity and positively regulates the inflammatory response of microglia in experimental autoimmune encephalomyelitis." (PMID 31766254, 2019). "Furthermore, C1ql3 is DE (>32-fold) with obesity, and inhibits insulin secretion and the expression of genes involved in β-cell function." (PMID 31300714, 2019). "Incretins, secreted from enteroendocrine cells, may play a critical role in the development of obesity by regulating insulin signaling in adipocytes, depending on the type of sweetener consumed." (PMID 31010163, 2019). "On the other hand, propionate may decrease liver fatty acid content and improve insulin sensitivity, providing benefits in the context of prevention of obesity and type 2 diabetes, as shown in mice." (PMID 31208043, 2019). "Further, if aspects of insulin and glucose metabolism are influencing central reward signaling, this presents the potential for personalized therapeutic targets in diseases of reward signaling and obesity." (PMID 30849082, 2019). "Adding a glucose lowering and insulin-sensitizing drug, such as metformin, has not shown a positive benefit/risk ratio, indicating that prevention of overweight, obesity is needed." (PMID 30849076, 2019). "Genetic activation of mTOR results in enhanced beta cell growth and increased insulin secretion in mouse beta cells, whereas pharmacological inhibition of mTOR dramatically inhibited insulin secretion and reduced beta cell mass in a rodent model of obesity." (PMID 30334081, 2019). "While the decrease in food intake upon acute activation of hypothalamic Gipr cells appears to be at odds with the protection of Gipr KO animals from diet-induced obesity, it is likely that the resistance to weight gain exhibited by Gipr KO mice is at least in part due to decreased insulin signaling." (PMID 31447324, 2019). "This raises the exciting possibility that PPP1R15A inhibition may be a potential therapeutic strategy in obesity with insulin resistance or in advanced states of the natural evolution towards diet-induced diabetes." (PMID 30814564, 2019). "In animal models of obesity, insulin transport across the BBB is impaired." (PMID 31213970, 2019). "Intriguingly, ER stress relievers such as tauroursodeoxycholic acid (TUDCA) and 4-phenylbutyric acid (PBA) increased muscle insulin sensitivity in patients with obesity, supporting the hypothesis of ER stress-mediated lipotoxicity in the skeletal muscle." (PMID 31330812, 2019). "The increases in lean mass and BMR combined with the decreases in VAT content after TRT + RT may improve cardiometabolic health, insulin sensitivity, and prevent obesity." (PMID 31443727, 2019).
Obesity (continued). "In a study on the Turkish population, the relationship between obesity, metabolic syndrome, and insulin-related parameters of the FTO gene’s rs9939609 and rs1421085 SNPs were investigated in 1967 individuals in the Turkish Adult Heart Disease and Risk Factors (TEKHARF) cohort." (PMID 31810473, 2019). "However, in the context of obesity, various processes including the dysfunctional lipid metabolism can affect insulin sensitivity and glycemic regulation." (PMID 31551816, 2019). "This may reflect a direct relation between hepatic inflammation and systemic insulin signalling but could also be explained by a subgroup of patients which is more prone to develop obesity-related consequences." (PMID 31470414, 2019). "Furthermore, it has been shown that mouse ovaries remain sensitive to insulin signaling while the pituitary gland becomes insulin resistant in a diet-induced obesity model." (PMID 31009498, 2019). "In conclusion, HFD-induced obesity causes AHR and peribronchial and perivascular lung fibrosis through the TGF-β1 pathway, and TGF-β1 can be produced by the bronchial epithelium via stimulation with insulin." (PMID 31133649, 2019). "Therefore, phosphorylation of IRS1 following the activation of JNK1 has a key role in the insulin resistance mechanism and obesity process in mammals." (PMID 31551756, 2019). "Indeed, acute ceramide depletion in adult mouse hepatocytes or adipocytes prevents and reverses hepatic lipid accumulation as well as improving systemic glucose tolerance and insulin sensitivity in diet-induced obesity mice." (PMID 31085992, 2019). "Besides macrophages, many other immune cells (e.g., dendritic cells, mast cells, neutrophils, B cells, and T cells) reside in adipose tissue during obesity, playing a key role in the development of adipose tissue inflammation and insulin resistance." (PMID 32063863, 2019). "In another mouse model of high-carbohydrate high-fat-diet-induced obesity, the cPLA2 inhibitor treatment attenuated visceral adiposity and improved most features of metabolic syndrome, including insulin sensitivity, glucose intolerance, and cardiovascular abnormalities." (PMID 31500176, 2019). "In summary, this indicates that the obesity-protected, insulin-sensitive, less inflamed phenotype of pLPHC diet mice is tightly associated with higher gut bacterial diversity, increased Bacteroidetes and Akkermansia and lower Proteobacteria and Desulfovibrionaceae." (PMID 31019501, 2019). "Several interventional studies evaluated the effects of drugs used in patients with MetS and T2-DM, namely insulin sensitizers and antidiabetic drugs, on testosterone levels and hypogonadism, and confirmed a strict relationship between obesity and hypogonadism." (PMID 31402895, 2019). "Hepatic steatosis is a feature related to obesity and impaired insulin sensitivity." (PMID 31744052, 2019). "In contrast, the insulin response to sucralose ingestion differed depending on the presence of obesity: decreased within 20–40 min of the OGTT in normal-weight participants but increased within 90–120 min in participants with obesity." (PMID 31877631, 2019). "Insulin increased glucose uptake in all cell lines, independent of their association, or lack thereof, with obesity." (PMID 31188872, 2019). "The insulin signaling pathway plays a key role in the normal genetic background with diet-induced obesity, but it seems to be not important in two genetic risk factors." (PMID 31795276, 2019). "In obesity, surprisingly, mice deficient for the IR specifically in myeloid cells exhibit a protective phenotype associated with decreased ATM accumulation and improved insulin sensitivity." (PMID 31497027, 2019). "Though small (n = 111), this comparison found significant improvements in the siblings born after gastric bypass in relation to lower levels of severe obesity, greater insulin sensitivity and improved lipid profiles compared to those born before the gastric bypass." (PMID 31656604, 2019).
Obesity (continued). "Ovariectomy in the female mPHB-Tg mice suggested a potential role of ovarian estrogens in protection from obesity-related metabolic dysregulation, as the ovariectomized mPHB-Tg mice developed impaired glucose homeostasis and insulin sensitivity similar to their male counterparts." (PMID 31118075, 2019). "Interestingly, we also show that the obesity and insulin resistant that was present in 18‐month‐old male mice is absent when the mice were again studied at 28 months of age, indicating that advancing age reduces adiposity and improves insulin sensitivity." (PMID 30706674, 2019). "Since obesity leads to pancreatic beta cell hyperplasia, the normal glucose tolerance of Ubi-LepRNull mice could be explained by an obesity-induced increase in insulin secretory capacity, overcoming their insulin resistance." (PMID 30694175, 2019). "For example, obesity-induced hyperleptinemia and increases in insulin/IGF-1 levels, as observed in the present study and in other models, can lead to activation of phosphoinositide 3-kinase and mammalian target of rapamycin (mTOR) signaling and promote primary tumor growth." (PMID 30867005, 2019). "The association between obesity and NAFLD is likely a consequence of the large sources of fatty acids in obese individuals, which originate from adipose tissue and are combined with the less effective insulin-mediated suppression of lipolysis." (PMID 31618320, 2019). "Excess production of acetate in the gut has been linked to altered insulin regulation and obesity, and excess energy production via microbial conversion of fiber to SCFA may contribute to obesity and cancer, for which dietary intake is an important mediator." (PMID 30758778, 2019). "Total insulin and glucose concentrations were greater in those with obesity compared with those of healthy weight (p < 0.05 for effect of group), and a greater response was seen overall after the high-carbohydrate compared with after the high-protein meal (p < 0.05 for effect of meal)." (PMID 30764560, 2019). "Our findings do not preclude the possibility that other approaches for clearing senescent cells or at different stages during development of obesity‐induced metabolic dysfunction might affect hepatic glucose production or pancreatic insulin secretion." (PMID 30907060, 2019). "DB gut signatures linked to metabolic syndrome seem to be associated to a particular phenotype microbial imbalance, that results in an increase in circulating LPSs with emerging pro-inflammatory responses, decreasing insulin signaling, and that favors adiposity and obesity." (PMID 31888137, 2019). "However, the functional contribution of miR-146a in adipose tissue inflammation and remodeling, glucose and insulin tolerance, and hepatic steatosis during the development of obesity remains to be elucidated." (PMID 31477775, 2019). "In addition, obesity increased insulin and insulin–like growth factor–1 levels, which would increase OC risk." (PMID 31640608, 2019). "Surprisingly, after 2, 4 and 8 weeks of high fat feeding to induce obesity, we did not observe any protection against loss of insulin sensitivity by iNOS absence, nor did we observe an overt, sustained, decline in liver mitochondrial function." (PMID 30716103, 2019). "Moreover, elevated NF-kB signaling in the hypothalamus of HFD rodents, triggers endoplasmic reticulum (RE) stress which promotes hypothalamic insulin resistance leading to the acceleration of obesity and T2D disease progression." (PMID 30906281, 2019). "The NF-κB target genes JUN, PIK3R1, FOS, and IGF1R are enriched in the insulin signaling pathway which could contribute to obesity related disorders." (PMID 31013288, 2019). "Indeed, in obesity and insulin resistance, β-cells are able to modulate the energetic metabolism in order to increase insulin synthesis and release." (PMID 31412623, 2019).